HES1 (hes family bHLH transcription factor 1)
Diseases named in the same sentence as HES1 in open-access papers (continued):
Sharing a sentence is not in itself a finding about the gene and the disease.
osteoporosis (3 papers, 2021 to 2025). A condition of reduced bone mass, with decreased cortical thickness and a decrease in the number and size of the trabeculae of cancellous bone (but normal chemical composition), resulting in increased fracture incidence. "The reduction in bone formation in ageing‐related osteoporosis was caused by decreased MACF1 level leading to disabled suppression of HES1 expression." (PMID 34133068, 2021). "All these results implied that MACF1 inhibited the expression level and activities of HES1, an osteogenic inhibiting factor in ageing‐related osteoporosis." (PMID 34133068, 2021). "Reports have shown that HES1 inhibited osteoblast differentiation, and its expression level was enhanced during ageing‐related osteoporosis." (PMID 34133068, 2021). "The results implied that HES1 expression and activity might involve in aging related osteoporosis." (PMID 34133068, 2021). "The results implied that MACF1 may relieve ageing‐related osteoporosis through inhibition of HES1." (PMID 34133068, 2021). "We have also found MACF1 negatively regulated HES1 expression and activities, which indicated a potential mechanism for MACF1 regulating ageing‐related osteoporosis." (PMID 34133068, 2021).
pulmonary fibrosis (3 papers, 2022 to 2024). Chronic progressive interstitial lung disorder characterized by the replacement of the lung tissue by connective tissue, leading to progressive dyspnea, respiratory failure, or right heart failure. "Enhanced Notch signaling was discovered during pulmonary fibrosis development, while the suppression of JAG1, Notch1, NICD, and Hes-1 neutralized the development of bleomycin-induced pulmonary fibrosis." (PMID 36499287, 2022). "MK activates the Notch2 signaling pathway, up-regulates the downstream target HES1 and promotes tumor cell proliferation while inhibiting tumor cell apoptosis Notch signaling has been found to be upregulated in pulmonary fibrosis, and inhibition of Notch significantly alleviated pulmonary fibrosis." (PMID 35774607, 2022).
renal carcinoma (3 papers, 2013 to 2020). A carcinoma arising from the epithelium of the renal parenchyma or the renal pelvis. "Knockdown of UCA1 increased DLL1, Jag1, Jag2 and Notch1expression and decreased DLL4, NICD and Hes1 expression in renal cancer cells." (PMID 31996265, 2020). "We found knockdown of UCA1 increased DLL1, Jag1, Jag2 and Notch1expression and decreased DLL4, NICD and Hes1 expression of renal cancer cells in vivo." (PMID 31996265, 2020). "Thus, the expression of Notch 1 and HES-1 proteins was more readily decreased in the Marimastat treated renal carcinomas than in those treated by DAPT." (PMID 23659326, 2013). "Interestingly, no significant change was observed in the expression of HES1, GLI1 and NANOG, whereas the expression of CTNNB1 was markedly increased, suggesting that CTNNB1 may be involved in increased renal cancer stem-like phenotype caused by the down-expression of PIK3R1." (PMID 25757764, 2015).
retinoblastoma (3 papers, 2016 to 2021). A malignant tumor that originates in the nuclear layer of the retina. "Expression of the Notch target Hes1 was evaluated by immunohistochemistry in 11 human retinoblastoma samples." (PMID 27661116, 2016). "We found that the Notch target Hes1 was highly expressed in most primary tumor samples, and all key pathway components were also present in both retinoblastoma lines examined." (PMID 27661116, 2016). "Moderate or strong nuclear expression of Hes1 was found in 10 of 11 human retinoblastoma samples analyzed immunohistochemically, supporting a role for Notch in retinoblastoma growth." (PMID 27661116, 2016). "Here we demonstrate protein expression of the Notch target Hes1 in primary tumors samples, and a functional role for Notch signaling in retinoblastoma cell lines, suggesting that Notch pathway represents a potential new target for the treatment of these aggressive childhood tumors." (PMID 27661116, 2016). "Meanwhile, if oscillatory gene expression in some undifferentiated cells/RPCs does not stop due to pathological events (e.g., mutations in genes regulating the stability of mRNA and proteins of genes like Notch1, Hes1, Dll1, Ascl1, Neurog2, etc.), these cells may begin retinoblastoma formation." (PMID 31607861, 2019). "This together with lack of expression of other well-known RPCs markers such as SOX2, SFRP2, HES1 and HES5, excludes RPCs as cell of origin for retinoblastoma." (PMID 34003213, 2021).
schizophrenia (3 papers, 2010 to 2019). A major psychotic disorder characterized by abnormalities in the perception or expression of reality. "Although Notch signaling is also involved in the functions of mature neurons in learning and memory and in the risk factors for mental disorders such as schizophrenia and bipolar disorder, the in-vivo role of Hes1 in mature neurons remains unknown." (PMID 31160641, 2019). "Quetiapine ameliorated the schizophrenia-like behaviors and decreased expression of myelin basic protein and inhibition of Notch signaling molecules, such as Notch1, Hes1, and Hes5, in the forebrain that induced by cuprizone." (PMID 26232790, 2015).
Sepsis (3 papers, 2018 to 2023). Sepsis is defined as life-threatening organ dysfunction caused by a dysregulated host response to infection. "We found that levels of NICD and its downstream regulator Hes1 in ECs were reduced during sepsis, which further impaired vascular permeability via the Akt signaling pathway." (PMID 37205094, 2023). "A novel mechanism of autophagy induced by synthetic iron oxide–based nanoparticles (SPIONs) in mononuclear cells through activation of the Cav1–Notch1/HES1 signal pathway promoted inhibition of inflammation in the sepsis and liver injury model." (PMID 35911737, 2022). "In lipopolysaccharide (LPS)-induced sepsis, the levels of Notch signaling molecules, including Notch1, Notch2, Hes1, and intracellular domain of Notch (NICD), were increased." (PMID 29867921, 2018). "Other studies showed that Cav1 coordinated and coupled with Notch1/HES1 in the liver tissue of LPS–induced septic mice, which promoted the production of IL–10 in macrophages, leading to inhibition of inflammation in a model of sepsis." (PMID 35911737, 2022).
ulcerative colitis (3 papers, 2014 to 2022). An inflammatory bowel disease involving the mucosal surface of the large intestine and rectum. "In addition, the interplay between inflammation and the NOTCH signaling has been amply reviewed and it has been reported that NOTCH1 and HES1 in co-operation with TNF-α can suppress PPAR-γ to play a crucial role in the pathogenesis of ulcerative colitis." (PMID 36386153, 2022).
virus infection (3 papers, 2010 to 2024). "Further study showed that viral infection upregulated the level of HES1 and HES5 mRNA expression and downregulated that of RBP-Jκ." (PMID 39530666, 2024). "The knockdown efficiency of Hes1 shRNA lentivirus vectors was not so high (about 30% reduction), because the virus infection rate was low due to cell clumps." (PMID 20545770, 2010). "However, the relationship between Hes1 regulation and virus infection, in particular whether and how HCMV regulates Hes1, remained unknown." (PMID 28750047, 2017).
anemia (2 papers, 2019 to 2024). A reduction in the number of red blood cells, the amount of hemoglobin, and/or the volume of packed red blood cells. "A recent study demonstrated that HES1 acts in concert with a Fanconi anemia protein, FANCD2 to suppress inflammation-induced PPARg to prevent HSC exhaustion." (PMID 39075526, 2024).
chronic myelogenous leukemia (2 papers, 2012 to 2016). "Notch signaling may also be involved in Chronic Myeloid Leukemia leukemogenesis through HES1, though this has not been experimentally validated." (PMID 24688641, 2012).
chronic obstructive pulmonary disease (2 papers, 2020 to 2024). A chronic and progressive lung disorder characterized by the loss of elasticity of the bronchial tree and the air sacs, destruction of the air sacs wall, thickening of the bronchial wall, and mucous accumulation in the bronchial tree. "Furthermore, HES1 appears to play a critical role in regulating lung fibroblast differentiation, and is known to be expressed in mucus cells from patients with chronic obstructive pulmonary disease, idiopathic pulmonary artery hypertension or IPF." (PMID 38540357, 2024).
dilated cardiomyopathy (2 papers, 2022 to 2025). Cardiomyopathy which is characterized by dilation and contractile dysfunction of the left and right ventricles. "Patients with hypertrophic cardiomyopathy (HCM) show higher expression of Notch2 and its target gene Hes1 in the left ventricle than patients with dilated cardiomyopathy." (PMID 40104444, 2025).
fibrosis (2 papers, 2012 to 2021). the formation of excess fibrous connective tissue in an organ or tissue in a reparative or reactive process. "In contrast, Notch signalling has also been reported to directly upregulate COL1A1 and COL1A2 promoter activity through a Hes1‐dependent mechanism in airway subepithelial fibrosis." (PMID 34363303, 2021). "The 50 mg/kg dose of DAPT significantly reduced the protein levels of Notch3-ICD and Hes1 as compared with fibrosis group (P<0.05)." (PMID 23056328, 2012).
gastric tumor (2 papers, 2022 to 2023). "Neck cell differentiation-related group C contained TFs such as Hes1, Pbx1, and Spdef, whereas isthmus progenitor cell-related group D again contained gastric tumor-related TFs such as Dnmt1 and Foxm1." (PMID 37386010, 2023).
glomerulosclerosis (2 papers, 2018 to 2019). A hardening of the kidney glomerulus caused by scarring of the blood vessels. "We observed clusters of HES1-expressing cells that were positive for the podocyte marker, Synaptopodin, at onset of glomerulosclerosis in mutants compared with controls." (PMID 29398135, 2018).
hemangioma (2 papers, 2011 to 2024). A benign vascular lesion characterized by the formation of capillary-sized or cavernous vascular channels. "Protein expression evaluation by immunofluorescence confirms that HEY2 is expressed by HemECs (CD31+ cells), while HEY1, HEYL, and HES1 are more widely expressed and mostly expressed by perivascular cells of hemangiomas." (PMID 21834989, 2011). "The Notch target gene Hes1 was also strongly downregulated in hemangioma ECs." (PMID 38402584, 2024).
infarction (2 papers, 2014 to 2025). A localised pathological necrosis of tissue resulting from obstruction of the blood supply usually by a thrombus, an embolus, or vascular torsion. "Hes1 levels increased towards the seventh day after infarction and following HT application before infarction." (PMID 39850112, 2025).
intrahepatic cholangiocarcinoma (2 papers, 2021 to 2025). A carcinoma that arises from the intrahepatic bile duct epithelium in any site of the intrahepatic biliary tree. "In intrahepatic cholangiocarcinoma (ICC), Hes1 gene knockout significantly inhibits tumorigenesis and progression." (PMID 40755759, 2025).
ischemic stroke (2 papers, 2021). A stroke disorder caused by obstruction of blood flow to the brain, due to thrombotic (local blood clot formation) or embolic (due to a blood clot or other material traveling from another site) event. "In addition, qPCR and western blot revealed that after ischemic stroke, the expression of Notch1, Jagged1, and Hes1 mRNA and Notch1, Jagged1, NICD, and HES1 protein was significantly increased at D1 and D3 in NDI group." (PMID 34305641, 2021).
lupus (2 papers, 2015 to 2016). "At last, we generated a TLR7 agonist-induced lupus mouse model, and confirmed that Notch-Hes-1 axis controlled TLR7-mediated autophagic death of macrophages via induction of P62." (PMID 27537524, 2016).
malignant glioma (2 papers, 2017 to 2023). A grade III or grade IV glioma arising from the central nervous system. "By performing differential expression analysis on our malignant glioma samples, we identified four DEGs, CD74, HES1, CALD1, and HEBP2, significantly upregulated in the AQP4 high expression group." (PMID 36599974, 2023).
medullary thyroid carcinoma (2 papers, 2017 to 2023). "Of particular importance is that miR-182 reveals its oncogenic capacity in medullary thyroid carcinoma by directly contributing to the invasive behavior through loss of the tumor suppressive HES1/Notch1 signaling circuit." (PMID 28122586, 2017). "MiR-182 has an oncogenic role in medullary thyroid carcinoma through regulation of the HES1/NOTCH1 axis." (PMID 37051101, 2023).
nasopharyngeal carcinoma (2 papers, 2015 to 2017). A carcinoma arising from the nasopharyngeal epithelium. "Our current study firstly revealed that Hes1 upregulation in a cohort of human nasopharyngeal carcinoma (NPC) biopsies is significantly associated with the EMT, invasive and metastatic phenotypes of cancer." (PMID 26452025, 2015). "Hes1, also considered as stem cell marker, is able to promote migration and invasion of nasopharyngeal carcinoma cells." (PMID 28076853, 2017).
osteoarthritis (2 papers, 2020 to 2025). A noninflammatory degenerative joint disease occurring chiefly in older persons, characterized by degeneration of the articular cartilage, hypertrophy of bone at the margins and changes in the synovial membrane. "This would be in agreement with previous work demonstrating important roles of HES1 and HES5 in chondrogenesis and cartilage development and of HES1 in preclinical models of osteoarthritis." (PMID 40345585, 2025). "Alteration of the osteoarthritis pathway due to RARγ agonist treatment was associated with the up-regulation of catabolic genes (ADAMTS5, HES1, and MMP13), inhibition of cartilage matrix anabolic genes (COL2A1, ACAN, and SOX9) and the up-regulation of death genes (CASP4)." (PMID 32294904, 2020).
Osteopenia (2 papers, 2019 to 2021). Osteopenia is a term to define bone density that is not normal but also not as low as osteoporosis. "Overexpression of Hes1 causes osteopenia in female mice, and inactivation of Hes1 in osteoblasts increases trabecular bone volume in male mice." (PMID 31281386, 2019). "We found that the osteopenia of Notch2tm1.1Ecan mice was ameliorated, and the enhanced osteoclastogenesis was reversed in the context of the Hes1 inactivation." (PMID 34742737, 2021). "Moreover, activation of HES1 in Ctsk-expressing cells led to osteopenia and enhanced osteoclast number, size, and bone resorptive capacity in BMM cultures." (PMID 34742737, 2021).
pancreatitis (2 papers, 2014 to 2015). Inflammation of the pancreas. "In the caerulein-induced pancreatitis mouse model, the expression of the exocrine genes disappeared in pancreatic exocrine cells, while genes normally associated with Notch components, such as Notch1, Notch2, Hes1, Jag2, and a low level of Dll1 were induced." (PMID 26729103, 2015). "However, in conditions associated with cell dedifferentiation and replication, such as experimental pancreatitis and exposure to cytokines, activation of Hes1 has been reported, and its expression was required for human β-cell proliferation in vitro." (PMID 24940737, 2014). "For instance, when the pancreas is injured by pancreatitis, the exocrine acinar cells lose their differentiated characteristics and present acino-ductal metaplasia, which strongly upregulates the expression of the receptors Notch1 and 2 and the target genes Hes1, Hey1, and Hey2." (PMID 26729103, 2015).
rectal adenocarcinoma (2 papers, 2021 to 2025). "Still, a statistically significant association was identified between HES1 relative expression levels and presence of mucinous component in the studied rectal adenocarcinomas (p= 0.022)." (PMID 34582650, 2021). "In the present study, HES1 and ATOH1 were inversely expressed in rectal adenocarcinomas with mucinous component." (PMID 34582650, 2021). "The current work studied gene expression of 3 CSCs related genes, namely LGR5, HES1, and ATOH1 in rectal adenocarcinomas among young Egyptian patients." (PMID 34582650, 2021). "Yet, both HES1 and ATOH1 expression levels were significantly correlated with presence of mucinous component in rectal adenocarcinomas." (PMID 34582650, 2021). "In rectal adenocarcinoma, an ETV4/Hes1/STAT3 signaling axis has been identified: the transcription factor ETV4 activates Hes1 transcription by binding to its promoter, which subsequently drives STAT3 phosphorylation to promote tumor proliferation and metastasis." (PMID 40755759, 2025).
rectal cancer (2 papers, 2021). A primary or metastatic malignant neoplasm that affects the rectum. "The study aimed to delineate the gene expression profile of LGR5, HES1 and ATOH1 in young Egyptian rectal cancer (RC) patients and investigate the correlation between expression profiles and clinical outcome." (PMID 34582650, 2021).
renal fibrosis (2 papers, 2018 to 2019). A final common manifestation of a wide variety of chronic kidney diseases characterized by glomerulosclerosis and tubulointerstitial fibrosis. "Hes1 represses ppargc1a during Notch-induced renal fibrosis; however, induced overexpression of ppargc1a can ameliorate this process." (PMID 30475208, 2018).
sarcoma (2 papers, 2023 to 2025). A usually aggressive malignant neoplasm of the soft tissue or bone. "In sarcoma immunoradiotherapy, elevated tumour‐associated macrophages (TAMs) expressing IL4I1/HES1 predict poor response, highlighting the need for combinatorial approaches targeting monocyte–macrophage axes." (PMID 40936181, 2025).
skin aging (2 papers, 2021 to 2023). The gradual irreversible changes in structure of skin that occur as a result of the passage of time.. "They found that the downregulation of KLF6 and HES1 were the driving force involved in skin aging." (PMID 36832881, 2023). "In addition, HES1 has been described to be downregulated in dermal fibroblasts upon UV radiation, a known mechanism of extrinsic skin aging." (PMID 35069694, 2021).
small intestinal adenocarcinoma (2 papers, 2020 to 2023). "Further elucidation of the underlying molecular mechanism of HES-1 will contribute to development of new therapeutic targets in patients with small intestinal adenocarcinomas." (PMID 32974155, 2020). "Correlation between clinicopathologic factors and HES-1 expression based on KRAS genotype in small intestinal adenocarcinoma patients." (PMID 32974155, 2020). "Correlation between clinicopathologic factors and HES-1 expression of small intestinal adenocarcinoma patients." (PMID 32974155, 2020). "In this study, we investigated the clinicopathologic and prognostic significance of HES-1 expression in small intestinal adenocarcinomas by utilizing combined immunohistochemistry (IHC) and digital image analysis." (PMID 32974155, 2020). "In addition, we examined the potential clinical significance of HES-1 expression in patients with small intestinal adenocarcinomas harboring mutant KRAS." (PMID 32974155, 2020). "Further studies are needed to clarify the relationship between HES-1 and KRAS genotype in small intestinal adenocarcinomas." (PMID 32974155, 2020). "The clinicopathologic and prognostic significance of HES-1 expression has not been elucidated in small intestinal adenocarcinoma." (PMID 32974155, 2020). "Materials and Methods: To investigate the clinicopathologic and prognostic implications of HES-1, HES-1 immunohistochemical expression was analyzed in digital images along with clinicopathological variables, including survival and KRAS genotype, in 185 small intestinal adenocarcinomas." (PMID 32974155, 2020).